CD38 (CD38 molecule)
Diseases named in the same sentence as CD38 in open-access papers (continued):
Sharing a sentence is not in itself a finding about the gene and the disease.
infection (continued). "To compare the ability of CD38+ and CD38- CD4+ T cells to produce IFN-γ, we assessed the frequency of IFN-γ positive cells induced by mitogenic stimulation in CD38+ and CD38- CD4+ T cell populations collected prior to and at peak infection seven days later." (PMID 27662621, 2016). "CD38+ CD4+ T cells stained negatively for the apoptotic marker Annexin-V and the viability stain propidium iodide (Pi) prior to infection (98.4±0.5% Annexin-V-, 99.8±0.5% Pi-) and during infection (98.8±0.8% Annexin-V-, 99.8±0.2% Pi-)." (PMID 27662621, 2016). "We found that CD38 expression was highly elevated on NK cells in PBMC during acute illness, but decreased during early convalescence and remained present on up to 40% of NK‐enriched cells 1 year after infection." (PMID 26439909, 2016). "Upon infection, the levels of pSTAT1 and pSTAT4 within both CD38+ and CD38- CD4+ T cells decreased, while the expression of pSTAT5 was significantly decreased in the CD38+ CD4+ T cell subset only." (PMID 27662621, 2016). "Additionally, the CD38+ CD4+ T cells contained a higher proportion of cells co-expressing perforin and granzyme B (p = 0.001 and p = 0.006 prior to and at peak infection, respectively." (PMID 27662621, 2016). "This could explain the variation observed in the pre-existing proportion of CD38+ cells among total CD4+ T cells between individuals (ranging from 0.9 to 10.9% of total CD4+ T cells), reflecting a more or less recent infection with a pathogen." (PMID 27662621, 2016). "The proportion of cells expressing granzyme B and/or perforin within either CD38+ or CD38- CD4+ T cell subsets did not change markedly during the course of infection." (PMID 27662621, 2016). "Consistent with this, CD38+ CD4+ T cells displayed significantly reduced levels of both pSTAT1 and pSTAT4 compared to CD38- CD4+ T cells (p = 0.016 and p = 0.031 prior to infection, and p = 0.0002 and p = 0.0002 post-infection for pSTAT1 and pSTAT4, respectively)." (PMID 27662621, 2016). "Similarly to previous reports, we found that a greater proportion of CD38+ CD4+ T cells expressed CD45RA in comparison to CD38- CD4+ T cells both prior to, and at peak infection." (PMID 27662621, 2016). "There were more CD38+ cells in the minor and severe infection groups than in the healthy and silent infection groups among CD4+ cells, but this difference was not statistically significant." (PMID 24646014, 2014). "Interestingly, levels of double positive HLA-DR/CD38 CD8 T cells in those patients, initiating ART early at the time of primary infection were similar to that measured in healthy seronegative controls." (PMID 23818854, 2013). "Next, we examined sires with or without local expression of human CD38 (HCD38) in the NAcc using a lentivirus infection method that had been described previously." (PMID 24059452, 2013). "Regardless of infection status, NK cells were uniformly CD38+ throughout most of infancy, expressed CD45RA and lacked expression of CD28 and CCR7 (data not shown)." (PMID 23293640, 2012). "High expression levels of lymphocyte activation marker (CD38), TLR2, macrophage inflammatory protein (CCL4) and osteopontin (SPP1) at 4 weeks that was sustained until 16 weeks of infection suggested an early and robust inflammation in the lungs in association with progression of the disease." (PMID 22645653, 2011). "On the other hand, NAMPT protein expression remains elevated during the later stages of infection and does not increase further alongside the rise in CD38 expression and activity, suggesting that NAMPT induction alone is insufficient to prevent the NAD+ decline in ZIKV-infected brains." (PMID 41362627, 2025).
infection (continued). "In the current study, the high CD38 expression in old murine BMMs after infection with oral pathogens was not directly correlated with the activation of NF-κB, PI3K, and MAPK protein kinases nor the amount of pro-inflammatory cytokine (IL-1β, IL-6, and TNF-α) released in old murine BMMs." (PMID 40649955, 2025). "The decrease of memory B cells, CD69+ and CD38+T cells, as well as the increase of PD-1+, CTLA-4+ of CD4+/CD8+T cells and double negative B cells, indicate that sustained immune responses against BA.5 infection may wane more rapidly in elderly populations." (PMID 40416973, 2025). "Therefore, under the complex immune changes, we explored whether those immune fluctuations in CD8+CD38+ and CD8+HLA-DR+ cells could distinguish infection among the endotypes." (PMID 38533498, 2024). "Only CD38+KLRG1-CD8+ T cells exhibited enriched overlap with a public database of SARS-CoV-2-specific TCR sequences, indicating that in both vaccination and infection, KLRG1 expression demarcated heterogeneous immune responses amongst activated and responding CD8+ T cells." (PMID 37735591, 2023). "Interestingly, CD4 and CD8 T cell activation mostly resolved in the peripheral blood by day 14 PI but CSF CD38 + HLA-DR + CD8 T cell frequency peaked at day 14 PI and remained elevated in 2 of 4 animals (when compared to each animals’ pre-infection level) at day 28 PI." (PMID 35130924, 2022). "What is more, CD38 is needed to mediate NAD+-dependent bacterial engulfment but also to rearrange the cytoskeleton in phagocytes and to perform adenosine diphosphate ribose-dependent signaling required for the migration of immune cells to the site of infection." (PMID 36077708, 2022). "As the AAV-LAV-BPIFB4 infection was able to remove from the blood the circulating senescent cells by redirecting them to the spleen and rescue NAD+ level, we asked if the effects of AAV-LAV-BPIFB4 might be related to the CD38 modulation." (PMID 35087020, 2022). "Similarly, in large phase 3 trials evaluating CD38 antibody daratumumab, rates of serious infections either did not increase, or increased only slightly, under antibody treatment." (PMID 35395951, 2022). "We observed higher expression of CD38, CD69 and CD40LG during active COVID-19 infection, indicating an activated phase of T cell population, compared to the healthy and the recovered, where the T cells are at resting phase in comparison to the active infection." (PMID 36532041, 2022). "Moreover, the frequency of CD38 and HLA-DR-coexpressing TIGIT+NK and TIGIT−NK cells, correlated positively with HIV-1 viral load, but had fewer CD4 T-cell counts in the first, third and twelfth month of infection." (PMID 33717085, 2021). "Further, CD8+ T cells were examined for additional activation marker CD38, which is involved in cell adhesion, signal transduction and calcium signalling, was found to be upregulated in convalescent patients but not during active infection." (PMID 34075347, 2021). "Among non-PMN myeloid cells, there were few CD38+CD14+ cells two weeks after infection." (PMID 32544188, 2020). "We thus hypothesized that CD38 may modulate P2X7 during nga(G330D) but not wt infection, as only wt bacteria would consume the substrate β-NAD+." (PMID 31275321, 2019). "The presence of CD38 ecto-nicotinamide nucleotidase in activated immune cells may reduce the availability of NAD+ to bacteria and other pathogens and could limit the development or progression of infections." (PMID 31214171, 2019). "Our discovery that CD38 is the main nicotinamide dinucleotide (NAD+) catabolic enzyme has shed light on the relevance of this enzyme in organismal NAD+ metabolism and has implications for several pathophysiological conditions including infection, aging, tumorigenesis." (PMID 31214171, 2019). "However, levels of CD38 were not significantly different between subjects with neuroinvasive infection and asymptomatic subjects." (PMID 26795118, 2016).
infection (continued). "We found that the proportion of CD45RA+ within CD38+ but not CD38- CD4+ T cells is significantly increased upon infection and CD38 has been shown to be preferentially expressed by CD45RA+ CD4+ T cells and might play a role for lymphocyte homing on those cells." (PMID 27662621, 2016). "Additionally, the frequency of Ki67+ cells decreased at 7 days post infection compared to prior to infection in CD38+ but not in CD38- CD4+ T cells." (PMID 27662621, 2016). "Furthermore, there was an increased in the frequency of CD45RA+ cells at 7 days post infection compared to prior to infection in CD38+ but not in CD38- CD4+ T cells." (PMID 27662621, 2016). "Thus, circulating CD38+ CD4+ T cells that expand during infection do not represent a specific subset of Tfh cells." (PMID 27662621, 2016). "Thus, the accumulation of CD38+ CD4+ T cells in the peripheral blood upon infection is not due to the recruitment of CD38- CD4+ T cell subsets into other body compartments such as lymphoid organs." (PMID 27662621, 2016). "This occurred via proliferation starting between day 3 and day 7 post infection, paralleling the polyclonal CD8+ T-cell response and peaking at around day 10, when ∼85% (IQR 70–92%) of epitope-specific CD8+ T cells in blood showed activation and proliferation by CD38 and Ki-67 expression." (PMID 26687547, 2015). "Infection with lentiviral vectors containing wild-type CD38, but not CD38-R140W, rescues the social recognition deficit of CD38 KO mice, suggesting R140W may be associated with social behavior." (PMID 24287856, 2013). "In contrast, CD11b+TMEM119- cells, corresponding to infiltrating macrophages, showed a significant increase in CD38 expression (1.43-fold, SD ± 0.17, p = 0.0042), supporting the idea that macrophages may contribute to the NAD+ depletion during the late stages of infection." (PMID 41362627, 2025). "Noticing the disappearance of Slamf9+ and Cd38+ macrophages after SARS-CoV-2 clearance at d14, we speculated that the specific transcriptional state of Slamf9+ macrophages may be induced by engulfment or infection of SARS-CoV-2, which needs to be further investigated." (PMID 39414783, 2024). "A study exploring the immune properties of gut-associated lymphoid tissue (GALT), the primary target of infection, evaluated the frequency and activation phenotype of T cells in GALT samples from 11 HICs and 15 HIV progressives and showed that T cells in GALT of HICs express HLA-DR but not CD38." (PMID 33820568, 2021). "However, while such a protective role would help explain the association between high CD38 expression levels and favorable prognoses in HIV-infected children, it may not offer an advantage for the control of infection in adults." (PMID 31963337, 2020). "Alternatively, CD4+ T cell activation might permit persistent low-level infection of these cells, in turn maintaining efficient stimulation of the HIV-specific immune response and thereby helping to control viral replication through inducing CD38−/HLA-DR+ profile." (PMID 25000587, 2014). "In the present study, we first determined if there were differences in CD38 and NAD+ levels between young and old murine BMMs with or without infection with the oral pathogens Aa or Pg." (PMID 40649955, 2025). "By contrast, the frequency of CD38++CD24++ Breg cells and of CD38++CD24- plasmablasts appeared to be unaffected by infection (not shown)." (PMID 39136010, 2024). "Along with CD38, CD274 (PD-L1) and CD40 also presented a higher expression in the IND group after infection although no significance was observed." (PMID 35873155, 2022). "In contrast to cytokines and NK cells, the frequency of activated CD69+ CD4+ and CD38+ CD8+ T cells remained higher in the convalescent phase, regardless of infection symptomatic or asymptomatic nature, compared to healthy controls." (PMID 34669281, 2021). "Our data shows that during primary infection, the proportion of CD8, but not CD4, T cells expressing CD38 was markedly elevated." (PMID 34149690, 2021).
infection (continued). "The infection of myeloid cells in vitro by Rv.mCherry was independent of CD14 and CD38 expression (middle row)." (PMID 32544188, 2020). "Analysis of plasma cells (CD19+CD38+CD138+) demonstrated the lack of effect of wt EBOV, but as much as 4-fold increase in their percentage after infection with EBOV/VP35m." (PMID 27930745, 2016). "Interestingly, even in the control group there was a correlation between HLA-DR/CD38 coexpression and modeled proliferation rate (data not shown), suggesting that these methodologies are sufficiently sensitive to demonstrate subclinical inflammation or infection in clinically “healthy” controls." (PMID 24803534, 2014). "In this state of MDA5+ DM, the cut-off of CD8+CD38+ cells and CD8+HLA-DR+ cells could distinguish ADM+ DM with or without infections, which might have a certain significance for clinical judgments and need more studies to validate." (PMID 38533498, 2024). "Those who recuperated from avian H7N9 IAV infection were reported to exhibit strong IFN-γ+CD8+ T cell responses, whereas those who died from infection had some or no IFN-γ-producing cells and showed protracted activation of exhausted PD-1-expressing CD38+HLA-DR+ CD8+ T cells." (PMID 36992177, 2023). "Despite this noted contraction of CD4+ T lymphocytes, the functionality of these cells does not appear to be impaired, since we observed an increase of CD38+CD4+ T cells in LbAgS cell cultures from BT and DT patients, indicating an activation profile of CD4+ T cells in patients presenting infection." (PMID 32203546, 2020). "Similarly, on day 5 and irrespective of infection status, PHA induced significantly elevated expressions of CD38+HLA-DR+ and CD38+HLA-DR-, but not CD38-HLA-DR+ on CD4+ T cells compared to the unstimulated infected control (p ≤ 0.0001)." (PMID 31396221, 2019). "Interestingly, a significant increase in the B220+GL7+CD95+CD38+ B-cell subset was observed in co-infected mice at 6 dpi, which was not present in CHIKV-infection only controls." (PMID 30254309, 2018). "There was a higher frequency of CD38+ CD4+ T cells but not CD38+ CD8+ T cells or B cells, and absolute numbers of CD38+ CD4+ T cells and B cells also increased in the peripheral blood during infection." (PMID 27662621, 2016). "Prior to infection, there was no significant increase in CD69 expression following TCR stimulation for both CD38+ and CD38- CD4+ T cells, although the basal expression of CD69 was higher on CD38+ CD4+ T cells." (PMID 27662621, 2016). "This increased expression at the peak of infection was confirmed by flow cytometry on six additional diagnosed individuals, showing that 18.6 ± 6.6% of activated (CD38+) MAIT cells expressed Ki67 at the peak of infection compared to 5.5 ± 2.0% of non-activated (CD38−) MAIT cells." (PMID 29343684, 2018).
cancer (253 papers, 2012 to 2026). A tumor composed of atypical neoplastic, often pleomorphic cells that invade other tissues. "Recently, the landscape of blood compatibility testing has been complicated due to the interference caused by therapeutic antibodies targeting CD38, a key target in cancer immunotherapy that is also expressed on red blood cells." (PMID 41497985, 2026). "On one hand, CD38 expression is associated with the recruitment of immunosuppressive cells, including Tregs and MDSCs, and studies indicate that CD38 facilitates cancer cell migration, proliferation and colony formation." (PMID 40547518, 2025). "We replace the cancer population with CD38+ and CD38- cancer cell subpopulations P and N, of which only P is susceptible to the drug." (PMID 40788967, 2025). "Emerging evidence highlights the association between CD38’s biological features and cancer progression, yet its mechanistic implications remain unresolved." (PMID 40529366, 2025). "Conversely, high densities of CD38+ macrophages have been linked to improved prognosis in certain cancers." (PMID 40547518, 2025). "This study identified increased age, reduced absolute counts of CD4+CD28− T cells, and elevated absolute counts of CD4+CD38− T cells as independent risk factors for CRF in pan-cancer patients, as determined by multivariate logistic regression analysis." (PMID 41018226, 2025). "Aberrant expression of CD38 has been associated with the progression of various cancers, including melanoma, glioblastoma, and hematologic malignancies." (PMID 39852780, 2024). "Preliminary cold dosing by unlabeled daratumumab allows redistributing further injected radioconjugates toward cancer cells; however, it should as well be associated with the risk of prolonged saturation of CD38 by antibodies devoid of radionuclides." (PMID 39466073, 2024). "CD38-expressing immune cells have been detected in the TME of numerous cancer types and are often associated with cancer progression." (PMID 37377962, 2023). "Telomere shortening and telomeric DNA damage induced by aging and cancer treatments can cause NAD+ depletion by activating PARP or increasing CD38 expression." (PMID 35801078, 2022). "In this context, the loss of CD38 expression to the MVs seems to be a way for the cancer to overcome CD38 therapeutic effects." (PMID 36139103, 2022). "CD4+ T‐cell counts, and percentages of CD8+ HLA‐DR/CD8+, CD8+ CD38+/CD8+ are associated with the cancer progression." (PMID 32459060, 2020). "These enhanced responses are associated with a more robust expression of CD38, a receptor that plays a role in activation and cytotoxicity, and NKp46, a receptor associated with a better response to influenza virus and certain cancers." (PMID 31708922, 2019). "We found that high expression of CD38 in normal and cancer tissues is associated with a 21% lower risk of recurrence (OR = 0.79, 95% CI 0.63–0.98, p = 0.037) compared to patients who do not have high CD38 in both." (PMID 30258629, 2018). "We analyzed a separate TMA for CD38 expression and observed a similar pattern, with high (above the median) expression for CD38 in both benign and cancer tissues associated with reduced risk of recurrence." (PMID 30258629, 2018). "Pathological analysis indicated that loss of CD38 increased cell death and reduced the amount of cancer-associated fibroblasts (CAFs) and blood vessels." (PMID 30159123, 2018). "Preliminary cold dosing by unlabeled daratumumab for saturation of FcRn receptors allows redistributing further injected radioconjugates towards cancer cells, however, it is as well associated with the risk of prolonged saturation of CD38 by antibodies devoid of radionuclides." (PMID 38826403, 2024). "CD38-SADA is a targeted radiotherapy delivering fixed doses of 177Lu-DOTA, a chelated complex of a lutetium radioisotope and dotatate, which leads to targeted emission of ionizing beta radiation against CD38+ malignant cells, resulting in DNA damage and associated cancer cell death." (PMID 39456582, 2024).